ENSG00000251545 (novel protein similar to SPATA31 subfamily E member 1 SPATA31E1)
Synonyms: LOC100289470
Gene: Protein-coding gene on chromosome 5 (179,522,483 to 179,525,074, forward strand). Ensembl gene ENSG00000251545.
Homologues: Paralogues in human: SPATA31E1 (27% identical), SPATA31A5 (24% identical), SPATA31A6 (24% identical), SPATA31A7 (24% identical), SPATA31A1 (23% identical), SPATA31A3 (23% identical), SPATA31C1 (22% identical), SPATA31C2 (22% identical), SPATA31D1 (22% identical), SPATA31D3 (19% identical), SPATA31D4 (19% identical), SPATA31F1 (15% identical), and 1 more.